LOXL2 (lysyl oxidase like 2)
Diseases named in the same sentence as LOXL2 in open-access papers (continued):
Sharing a sentence is not in itself a finding about the gene and the disease.
melanoma (continued). "Conversely, we found upregulation of LOX and other LOXL family members, especially LOXL2 and LOXL3, in several human melanoma cell lines." (PMID 30701028, 2018). "Both LOXL2 and LOXL3 are commonly expressed in melanoma cell lines." (PMID 41250755, 2025). "In summary, both LOXL2 and LOXL3 are frequently overexpressed in melanoma." (PMID 41250755, 2025). "Notably, BAPN has also been reported to inhibit the activity of other LOX family members, of which LOXL2 and LOXL3 were found to be expressed by both melanoma cells and fibroblasts, making the interpretation of the results complicated." (PMID 30701028, 2018). "Interestingly, LOXL2 and LOXL3 were found to be expressed in nearly all the melanoma cell lines studied." (PMID 30701028, 2018). "On the contrary, LOX and especially LOXL2, LOXL3, and LOXL4 were found to be upregulated in several human melanoma cell lines, and LOX inhibitor B-aminopropionitrile inhibited the invasive growth of these cells particularly when co-cultured with fibroblasts in Matrigel." (PMID 30701028, 2018). "Altogether, therapeutic targeting of the LOX family members, especially LOX and LOXL2, by promoting the tumor suppressive function of LOX and/or inhibiting the activity or expression of these enzymes, may offer viable ways to combat melanoma and other cancers." (PMID 30701028, 2018). "As LOXL2 was one of the most highly upregulated genes in melanoma cells compared to normal melanocytes, we were interested to investigate the role of all LOX family members in melanoma cells." (PMID 30701028, 2018). "Further functional analysis showed that poorly differentiated BRAFi-resistant melanoma cells also display a CAF-like phenotype characterized by the upregulation of typical myofibroblast and pro-fibrotic markers, including α-SMA, caveolin 1, MLC2, TAGLN2, FAPα and LOXL2." (PMID 36774337, 2023). "In addition, LOXL2 mRNA expression levels were significantly upregulated (fold 2.0; p = 0.0012) in the metastatic compared to non-metastatic primary melanomas." (PMID 30701028, 2018).
liver cancer (10 papers, 2019 to 2024). An epithelial or non-epithelial malignant neoplasm that arises from the liver. "The knock-down and inhibition of LOXL2 enhanced cellular senescence in lung and liver cancer cells, as confirmed by SA-β-Gal staining and quantitative RT-PCR analyses." (PMID 38922489, 2024). "Based on the HPA database, the results of IHC in lung, breast, and liver cancer tissues and corresponding normal tissues revealed that LOXL2 protein was predominantly localized in the nucleus and ECM." (PMID 38922489, 2024). "The SA-β-Gal staining results indicated that knock-down of LOXL2 facilitated cellular senescence in lung and liver cancer cells." (PMID 38922489, 2024). "LOXL2 functions as an oncoprotein in liver cancer, driving liver cancer cell proliferation, migration, invasion, and cell survival." (PMID 37253718, 2023). "LOXL2 can also confer additional effects on developmental regulation, aging, tumor (prostate and liver cancer) inhibition, cell growth control, and chemotaxis to each member of the family." (PMID 31382519, 2019). "In addition, knockdown of LOXL2 induced apoptosis and cell cycle arrest in liver cancer stem cells." (PMID 38475870, 2024). "In Hepatocellular cancer (HCC)/liver cancer (LiC) cells, the integrin β1/α5/JNK/c-JUN signaling pathway participates in higher matrix stiffness, which is induced by LOXL2 (lysyl oxidase homolog 2)." (PMID 37384249, 2023).
cervical cancer (9 papers, 2012 to 2024). A primary or metastatic malignant neoplasm involving the cervix. "To identify the clinical characteristics associated with LOXL2 expression in cervical cancer, we arranged LOXL2 expression and diagnostic age of the 176 core-set samples, which were ordered by LOXL2 expression." (PMID 32211324, 2020). "More importantly, increased expression of LOXL2 was significantly associated with decreased survival in cervical carcinoma, which was further associated with EMT phenotype in vitro." (PMID 32211324, 2020). "In this study, we found that LOXL2 highly expressed in carcinoma tissue, with 14 CpG islands of LOXL2 promoter that were significantly and negatively associated with its expression in cervical carcinoma." (PMID 32211324, 2020). "HIF-1 induction of LOX and LOXL-2 has been shown to promote migration in primary renal epithelial, and in breast and cervical cancer cells, which was associated with decreased E-cadherin expression." (PMID 23259746, 2012). "And we showed the clinical and molecular associations as well as functionally altered features of LOXL2 expression, which may drive carcinogenesis and potentially serve as a therapeutic target in cervical carcinoma." (PMID 32211324, 2020). "The authors then investigated the relationship between LOXL2 expression and LOXL2 promoter DNA methylation, finding that 14 CpG islands of LOXL2 were significantly and negatively correlated with LOXL2 gene expression in cervical cancer." (PMID 39684425, 2024). "High levels of LOXL2 expression were linked to worse overall survival (OS) and disease-free survival (DFS) in cervical carcinoma." (PMID 39684425, 2024). "In cervical cancer cells, circ0000228 sequesters miR-195 and upregulates LOXL2 expression to promote cervical cancer malignancy." (PMID 37762708, 2023). "Result showed that LOXL2 knockdown blocked cell division instead of promoting cell death in cervical cancer." (PMID 32211324, 2020). "We found that the expression of LOXL2 was positively correlated with EMT phenotype in cervical cancer, and the proliferation and migration of cells were attenuated after LOXL2 silencing." (PMID 32211324, 2020). "As LOXL2 expression status was correlated with molecular characterizations of cervical cancer, we performed cancer survival analysis for the two clusters." (PMID 32211324, 2020). "We firstly tested the LOXL2 expression pattern in 50 paired normal cervix and cervical carcinoma via qPCR and immunohistochemistry, and the LOXL2 expression pattern was found to be in accordance with public datasets from Gene Expression Omnibus (GEO)." (PMID 32211324, 2020). "Similarly, lncKCNQ10T1 enhances LOXL2 mRNA levels by blocking miR-1270, leading to decreased apoptosis of cervical cancer cells." (PMID 37762708, 2023). "By ordering the 176 core-set cervical cancer samples by LOXL2 expression, we found that the somatic alteration density was high in the low-LOXL2 cluster when considering the top 50 (P = 4.24585E-05), top 1-10 (P = 3.40597E-05), top 21-30 (P = 0.048011) mutation genes in the dataset." (PMID 32211324, 2020). "And there was specificity of LOXL2, high LOXL2 expression both in epithelial and stroma, which could be conducive to the epithelial–stromal cross talk and the malignant progression of cervical cancer." (PMID 32211324, 2020). "Therefore, we analyzed the poor prognosis of high-LOXL2 cluster in cervical cancer, such as EMT phenotype in cancer progression." (PMID 32211324, 2020). "Furthermore, these results showed the same tendency of LOXL2 positively correlated genes in cervical carcinoma, which was associated with ECM structural constituents." (PMID 32211324, 2020). "It should be noted that, in this study, we has examined only the expression pattern of LOXL2 in cervical carcinoma or paired normal tissue, the specific application and the significance in clinical samples should be further accessed, such as routine immunostaining." (PMID 32211324, 2020).
cervical cancer (continued). "Overall, we demonstrated the correlation between LOXL2 expression status and cancer molecular characterizations of cervical carcinoma, and identified LOXL2 may serve as a therapeutic target for such carcinoma." (PMID 32211324, 2020). "For the different mean expression patterns of APOBEC3 genes between the two LOXL2 clusters observed in our research and their negative correlation in the SiHa and HeLa cell lines, we tentatively put forward LOXL2 may be a trigger of APOBEC3 gene dysregulation in cervical cancer." (PMID 32211324, 2020). "In addition, LOXL2 also expression in the adjacent stroma of cervical cancer slide." (PMID 32211324, 2020). "We identified ED13, CTHRC1, LOXL2 and COP9 as cell invasion molecules impacting tumour progression in the ECM of endometrial and cervical cancer." (PMID 36982551, 2023). "We found that the LOXL2-interference resulted in an increase in APOBEC3A, APOBEC3B, APOBEC3D, and APOBEC3G protein levels in the cervical cancer cells." (PMID 32211324, 2020). "To validate the expression patterns of APOBEC3 genes and LOXL2, we carried out correlation analysis using the GEPIA dataset, which included expression profiles of 306 cervical cancer tissues." (PMID 32211324, 2020). "In addition, high LOXL2 expression was significantly correlated with poor OS and DFS in cervical cancer." (PMID 32211324, 2020). "High LOXL2 expression was found to be significantly correlated with poor OS (HR = 2.3, p(HR) = 6e−04) and with poor DFS (HR = 2.2, p(HR) = 0.0081) in the 292 cervical cancer TCGA dataset from GEPIA." (PMID 32211324, 2020).
heart failure (9 papers, 2016 to 2024). Inability of the heart to pump blood at an adequate rate to meet tissue metabolic requirements. "The product of the cuproptosis-associated gene LOXL2 is probably involved in myocardial fibrosis in patients with diabetes, which leads to the development of cardiac insufficiency." (PMID 38883603, 2024). "Deletion of Loxl2 causes incomplete perinatal lethality due to heart failure, whereas Lox-targeted mice died after birth due to cardiovascular instability." (PMID 35628534, 2022). "One study found an association between LOXL2 levels and cardiac fibrosis in heart failure (HF)." (PMID 36159334, 2022). "First, the high-glucose environment upregulates the PI3K/Akt/FoxO1/LOXL2 pathway, leading to the development of myocardial fibrosis and then heart failure." (PMID 38883603, 2024). "In summary, in the present study, we have shown that the cuproptosis gene LOXL2 is likely to be involved in the development of heart failure in patients with diabetes, with a putative mechanism as follows." (PMID 38883603, 2024). "Previous studies show that LOXL2 is elevated in the serum of heart failure or atrial fibrillation patients." (PMID 36159334, 2022). "This serum LOXL2 is likely secreted from fibroblasts in the cardiac interstitium, supported by the high expression of LOXL2 in the cardiac interstitium of heart failure patients." (PMID 36159334, 2022). "LOXL2 perturbed epithelial-mesenchymal transition, extracellular matrix deposition, themselves become factors that exacerbate the heart failure state." (PMID 35604403, 2022). "Serum LOXL2 levels were also elevated in patients with heart failure with preserved ejection fraction (HFpEF; 127±13 pg ml−1, n=25) compared with the control subjects (73±4 pg ml−1, n=24; Student's t-test, P<0.0001)." (PMID 27966531, 2016). "To determine a causative role of Loxl2 in interstitial fibrosis and heart failure, we used a LOXL2-specific neutralizing monoclonal antibody (AB0023, α-LOXL2; refs 6, 14) to inhibit Loxl2 activity in TAC-stressed mouse hearts." (PMID 27966531, 2016). "LOXL2 is also elevated in the serum of heart failure (HF) patients, correlating with other HF biomarkers, suggesting a conserved LOXL2-mediated mechanism of human HF." (PMID 27966531, 2016). "Aberrant expression and activity of lysyl oxidase-like 2 (LOXL2) as a secreted copper- and quinone-dependent enzyme is involved in pathological processes predominantly associated with the ECM remodeling, such as Wilson's disease, heart failure and cholestasis." (PMID 36209516, 2022). "Additionally, lysyl oxidase like-2 (LOXL2) activation is essential for cardiac fibrosis and heart failure development in animal and human models." (PMID 35604403, 2022). "Similarly, LOXL-2 is upregulated in diseased human hearts and elevated serum levels of LOXL-2 are found in patients with heart failure, suggesting it might be used as a biomarker for heart failure." (PMID 30742931, 2020). "Similarly, LOXL2 acts downstream of the transforming growth factor-beta (TGF-β) signaling which exacerbates myocardial fibrosis and heart failure induced by abdominal aortic coarctation in rats." (PMID 35604403, 2022).
atrial fibrillation (8 papers, 2017 to 2025). A disorder characterized by an electrocardiographic finding of a supraventricular arrhythmia characterized by the replacement of consistent P waves by rapid oscillations or fibrillatory waves that vary in size, shape and timing and are accompanied by an irregular ventricular response. "Moreover, LOXL2 expression was also detected in serums of idiopathic pulmonary fibrosis disease, rheumatoid arthritis-associated interstitial lung disease and was positively correlated with atrial fibrosis in patients with atrial fibrillation." (PMID 35246120, 2022). "Furthermore, LOXL2 expression was positively correlated with atrial fibrosis in patients with atrial fibrillation." (PMID 39877633, 2025). "Similarly, in a study performed by Zhao, it was argued that serum LOXL2 levels were positively correlated to the degree of left atrial fibrosis in Atrial fibrillation (AF) patients." (PMID 32703998, 2020). "Therefore, our results suggest LOXL2 as a contributing factor for cardiac hypertrophy, thus providing LOXL2 as a therapeutic target for cardiovascular diseases with cardiac hypertrophy and deregulated TGF-β1/Smad3 pathway, including atrial fibrillation." (PMID 36159334, 2022).
head and neck squamous cell carcinoma (8 papers, 2018 to 2025). A squamous cell carcinoma that arises from any of the following anatomic sites: lip and oral cavity, nasal cavity, paranasal sinuses, pharynx, larynx, and salivary glands. "Lysyl oxidase-like 2 (LOXL2) is more abundant in hypoxic exosomes than it is in normoxic ones in head and neck squamous cell carcinoma cells." (PMID 40534881, 2025). "Tumour-suppressive miR-26a/b, miR-29a/b/c, and miR-218 collectively downregulate LOXL2 mRNA in head and neck squamous cell carcinoma and prostate cancer cell lines." (PMID 37762708, 2023). "In this sense, the evaluation of LOXL2 levels in serum exosome fractions from head and neck squamous cell carcinoma patients supported the correlation between elevated LOXL2 and low-grade tumours." (PMID 37762708, 2023). "For example, LOXL2 fosters the tumorigenesis of head and neck squamous cell carcinoma through FAK/Akt signaling." (PMID 35309127, 2022). "Small extracellular vesicles (sEVs) derived from the hypoxic tumor microenvironment of head and neck squamous cell carcinoma (HNSCC) recruited MDSCs to form a premetastatic niche by delivering lysyl oxidase like 2 (LOXL2) to fibroblasts to induce fibronectin production." (PMID 35003065, 2021). "MiR-29a, accompanied with other tumor-suppressive miRNAs, such as miR-26a/b, miR-29b/c, and miR-218, apparently inhibited the migration and invasion of head and neck squamous cell carcinoma (HNSCC), via directly up-regulating LOXL2." (PMID 29217524, 2018). "In head and neck squamous cell carcinoma (HNSCC), these miRNAs were found to inhibit migration and invasion through targeting of the focal adhesion laminin–integrin pathway (LAMC2, ITGA6 and LOXL2)." (PMID 31906022, 2019).
Myocardial fibrosis (8 papers, 2017 to 2025). "Randomization (1:1) to CR + usual care vs. usual care will be stratified by baseline LOXL2 and myocardial fibrosis burden (LGE extent and/or ECV by T1 mapping)." (PMID 41007790, 2025). "Taken together, these results suggest that LOXL2 plays an important role in myocardial fibrosis in diabetes, which occurs secondary to the high-glucose environment and is mediated through FoxO1." (PMID 38883603, 2024). "Another study also showed that hyperactivation of the PI3K/Akt/FoxO1/LOXL2 pathway promotes the development of myocardial fibrosis in the cardiomyocytes of patients with diabetes." (PMID 38883603, 2024). "Lysyl oxidase-like 2 (LOXL2) is reported to be involved in many fibrotic diseases, including lung and myocardial fibrosis." (PMID 36979636, 2023). "This leads to myocardial fibrosis by the induction of transcription factor binding, which promotes the expression of genes such as LOXL2." (PMID 32824630, 2020). "PI3K is an upstream regulator of LOXL2, suggesting that this miR-375 may be involved in LOXL2-induced myocardial fibrosis." (PMID 38883603, 2024). "The cardiac expression of VEGFA was found to significantly positively correlate with that of LOXL2 in the present study, which may be associated with the stimulation of microangiogenesis in response to LOXL2-induced myocardial fibrosis." (PMID 38883603, 2024). "As LOXL2 is a biomarker for fibrosis, the increased level of LOXL2 in AF patients may indicate the involvement of LOXL2 in myocardial fibrosis and the progression of AF." (PMID 29089463, 2017). "Thus, a number of miRNAs are associated with diabetic heart failure and cuproptosis, and miR-375 likely interacts with LOXL2 and participates in the development of myocardial fibrosis, while also having an anti-fibrotic effect in combination with miR-27b-3p in exosomes." (PMID 38883603, 2024). "However, 12 weeks of aerobic exercise could significantly reduce the expression of LOXL2 and the downstream molecules in the heart of early aged hypertensive rats and this effect is related to the inhibition of myocardial fibrosis." (PMID 35604403, 2022). "Knockdown in H9c2 cells, utilising siRNA of either LOXL2 or ETFβ, revealed a decrease in the expression of Collagen Type I Alpha1 (COL1A1), a marker known to contribute to enhanced myocardial fibrosis." (PMID 32703998, 2020).
ovarian carcinoma (8 papers, 2015 to 2026). A malignant neoplasm originating from the surface ovarian epithelium. "LOXL2 promoted migration and invasion of ovarian cancer cells and metastasis of transplanted tumors in the xenograft mouse model." (PMID 41807828, 2026). "Our previous research revealed that collagen type I alpha 1 (COL1A1)-induced upregulation of lysyl oxidase-like 2 (LOXL2) was markedly overexpressed in ovarian cancer tissue samples and ascites." (PMID 41807828, 2026). "Further studies are needed to determine the cellular location of LOXL2 in ovarian cancer cells." (PMID 33058284, 2020). "Hence, LOX and LOXL-2 inhibition is a promising therapeutic target for ovarian cancer." (PMID 35054220, 2021). "In ovarian cancer, KDM4B is induced under hypoxia, and deletion of KDM4B increases H3K9me3 level at target gene promoters such as the LOXL2, LCN2, and PDGFB promoters, thereby inhibiting the invasion, migration and globulization of ovarian cancer cells." (PMID 35186950, 2021). "Our findings confirmed the molecular mechanism by which COL1A1-induced upregulation of LOXL2 promotes ovarian cancer metastasis through a positive feedback loop involving EGFR-MEK-ERK-SP1, offering novel scientific insights and potential therapeutic targets for inhibiting ovarian cancer metastasis." (PMID 41807828, 2026). "Combined with our correlation data between OSMR and LOXL2 mRNA in glioblastoma, prostate, and ovarian cancer patients, it is possible that OSM induces LOXL2 in multiple types of cancer and these patients could also benefit from a therapeutic targeting OSM induction of LOXL2." (PMID 34011405, 2021). "However, no study has explored the function of LOXL2 in ovarian carcinoma." (PMID 33058284, 2020).
squamous cell carcinoma (8 papers, 2009 to 2025). A carcinoma arising from squamous epithelial cells. "The regulatory role of miR-29 has also been reported to limit lysyl oxidase-like 2 protein (LOXL2) in squamous cell carcinoma." (PMID 34445276, 2021). "For this purpose, we analysed the stroma of DMBA/TPA-induced papillomas (n = 14 control, n = 2 Loxl2-KO, n = 10 Loxl2-KI) and squamous cell carcinomas (SCC) (n = 4 control, n = 2 Loxl2-KO, n = 1 Loxl2-KI) by H&E, Herovici and Picrosirius Red staining." (PMID 29953488, 2018).